HDAC1 (histone deacetylase 1)
Diseases named in the same sentence as HDAC1 in open-access papers (continued):
Sharing a sentence is not in itself a finding about the gene and the disease.
breast cancer (continued). "The anti-proliferative effect of HDAC inhibition in breast and prostate carcinoma cells reported here is a common feature of HDAC1/2 inhibition that has been observed preclinically in other tumor types, as well as in breast cancer patients treated with vorinostat." (PMID 26862729, 2016). "Previously, PN was shown to specifically inhibit HDAC1 in breast cancer cells." (PMID 26824319, 2016). "Importantly, a relative higher co-expressed rate of RXR-α and HDAC1 (54%) was also found in breast cancer tissues." (PMID 25762635, 2015). "Interestingly, vorinostat, which inhibits Hdac1, also inhibits brain metastatic colonization in a breast cancer model." (PMID 25004123, 2014). "Other studies have described a prognostic role for HDAC1 in breast cancer." (PMID 23627572, 2013). "Furthermore, it has been independently reported that the expression of either MBP-1 or HDAC1 is a predictor of good disease-free survival, and both proteins are independent prognostic factors in breast cancer patients." (PMID 23421821, 2013). "Interestingly, Snail2 has been described to repress several genes through recruitment of CtBP1 and HDAC1 to their proximal promoters in human breast carcinoma cells but the Snail2 regulatory regions involved in those interactions have yet to be defined." (PMID 22567133, 2012). "The expression patterns of miR-449a and of HDAC-1, in our cohort, are anti-correlated (Pearson's r = −0.26) and it might be that the mechanism is similar in breast cancer." (PMID 21364938, 2011). "Overexpression of HDAC1 has been seen in gastric and breast cancers." (PMID 16638127, 2006). "HDAC1 overexpression occurs in gastric cancer and modulates breast cancer progression." (PMID 16638127, 2006). "Interestingly, several other HDAC1/7-SE upregulated targets, such as SNPH, CCANG4, PREX1, IGFBP5, IL34 and BCAS4 also demonstrate remarkable level of breast cancer associated over-expression, providing additional support for the relevance of the ET-125 signature." (PMID 36038558, 2022). "In fact and in accordance with the present study, elevated HDAC-1 expression was associated with absence of axillary lymph node involvement, smaller tumor size, well tumor differentiation and better disease-free and overall survival in breast cancer." (PMID 26502922, 2015). "HDAC1 and HDAC2 (ranked at 3 and 4), among class I HDACs, were reported to regulate the changes in histone acetylation and were associated with HDAC inhibitors that were expected to reverse hypoacetylation levels observed even at the early stages of breast cancer progression." (PMID 21799737, 2011). "HDAC1, HDAC2, and HDAC8 were found to form a complex with EMT-TF Snail and induce EMT in breast cancer cells to promote migration." (PMID 40165290, 2025). "Recently, TBX2 was also shown to repress NDRG1 and CST6 in breast cancer by recruiting a CoREST repression complex (LSD1, ZNF217 and HDAC1) to their promoters." (PMID 39912718, 2025). "In breast cancer, TET2 recruits HDAC1/2 to remove H3K27ac at the CD274 promoter, thereby repressing its transcription." (PMID 41409271, 2025). "As anticipated, the combined BSp + Ash diet significantly declined the expression of HDAC1 and DNMT3A in mammary tumors." (PMID 38802425, 2024). "This study emphasized specific role of epigenetic modifiers like DNMT1 and HDAC1 & HDAC2 on proliferation and apoptosis, as well as aggressiveness, invasion and metastasis in terms of EMT through centrosome amplification in breast cancer." (PMID 36774386, 2023). "We observed variations in the expression levels of HDAC1, HDAC2, HDAC3 and HDAC10 mRNAs targeted by chidamide among the ER+ breast cancer cell lines." (PMID 37445654, 2023).
breast cancer (continued). "Correlation of the function of certain genes with underlying cellular metabolites was interpreted by observing cell survival and migration pattern of MDA-MB-231 breast cancer cells after knockdown of DNMT1 and specific inhibition of HDAC1 & HDAC2." (PMID 36774386, 2023). "The present study aims to correlate the expression of H3K9Ac, H4K12Ac, HDAC1, HDAC2 and HDAC6 in simple mammary carcinomas in dogs with clinicopathological parameters and overall survival time." (PMID 38028583, 2023). "Immunohistochemical expression of H3K9Ac, H4K12Ac, HDAC1, HDAC2 and HDAC6 in 61 samples of simple mammary carcinoma in female dogs." (PMID 38028583, 2023). "Oncomine data analysis revealed that most HDACs, including HDAC1, HDAC3, HDAC5, HDAC7, HDAC10, and HDAC11, are upregulated in luminal breast cancer subtypes." (PMID 35453496, 2022). "HnRNP A1 affects the expression of SREBP1, suppresses E-cadherin, and promotes formation of the Snail/HDAC1/2 complex by regulating the processing of miRNA-18a (pri-mir-18a), leading to EMT in breast cancer cells." (PMID 36052258, 2022). "When miR-18a expression is reduced, SREBP1 overexpression occurs, E-cadherin is suppressed, Snail/HDAC1/2 complex formation occurs, and EMT is ultimately induced in breast cancer cells." (PMID 36052258, 2022). "Our analysis confirmed the down-regulation of RPL13, and newly identified down-regulation of HDAC1, ANP32A, and the up-regulation of SNX2 as having the worst prognostic effects in normal-subtype breast cancer tumors (panels C4–C7)." (PMID 35971177, 2022). "Mechanistically, NKX2-8 directly interacted with HDAC1 on the PTHrP promoter, which resulted in a reduction of histone H3K27 acetylation, consequently transcriptionally downregulated PTHrP expression in breast cancer cells." (PMID 35707355, 2022). "Previously, we reported that HDAC1 and HDAC7 individually upregulate 1512 and 812 genes respectively in breast cancer cells." (PMID 36038558, 2022). "To interrogate the efficacy of HIF1α/HDAC1/EZH2 inhibitors in vivo, we used the immune-competent syngeneic 4T1 murine breast tumor model that closely mimics human TNBC breast cancer tumorigenesis." (PMID 35840558, 2022). "They revealed the high expression levels of these class I HDACs, and IHC results for HDAC1, HDAC2, HDAC3, and HDAC8 were positive in 17 (85%), 20 (100%), 20 (100%), and 17 (85%) of 20 breast cancer cases, respectively." (PMID 36188615, 2022). "Individual HDACs have been reported to be overexpressed in tumors, such as HDAC1 in prostate, gastric, colon, and breast cancer, and HDAC6 in breast cancer, suggesting that aberrant expression of HDACs is largely related to cancer." (PMID 36505774, 2022). "In fact, HDAC1, HDAC2, HDAC3, HDAC6, and HDAC7 have been shown to be overexpressed in breast cancer." (PMID 33738256, 2021). "SREBP1 recruited Snail/HDAC1/2 repressor complex to inhibit E-Cadherin expression, thereby suppressing epithelial-mesenchymal transition (EMT) in breast cancer." (PMID 34285190, 2021). "The HDAC1 and HDAC2 expression levels were constitutively very high in these breast cancer cell lines, comparing to the normal breast epithelial cells MCF-12F." (PMID 33498667, 2021). "The breast cancer subnetwork is found to contain (i) valid biomarkers including PIK3CA, PTEN, BRCA1, AR and EGFR; (ii) validated drug targets TOP2A, CDK4, HDAC1, IL6, BRCA1, HSP90AA1 and AR; (iii) synergistic drug targets EGFR and BIRC5." (PMID 35053185, 2021). "Totally, we explored a potential mechanism that FBXL10/SNAI1/HDAC1 axis promoted EMT and metastasis of breast cancer cells." (PMID 34718323, 2021). "Curcumin has been reported to inhibit HDACs such as HDAC1 and HDAC2 in breast cancer cell lines, MCF-7 and MDA-MBA-231." (PMID 33498667, 2021). "In keeping, we showed that ZNF750 negatively regulates cell migration and invasion in breast cancer cells; in particular, ZNF750 binds and recruits KDM1A and HDAC1 on the LAMB3 and CTNNAL1 promoters." (PMID 33298895, 2020).
breast cancer (continued). "In breast cancer, SREBP1 regulates the EMT by forming a co-repressor complex with HDAC1/2 and Snail1 to suppress E-cadherin and promote tumor metastasis." (PMID 32850856, 2020). "HDAC1, HDAC2, and cytoplasmic HDAC3 all displayed typical oncogenic characteristics and were independent prognostic factors for the overall survival of breast cancer patients." (PMID 32686908, 2020). "Next, to re-confirm the results shown with the involvement of HDAC1 and HDAC3 in breast cancer cell death, we observed the morphological changes using a phase contrast microscope." (PMID 32455774, 2020). "It has been reported that S6K1 mediates the phosphorylation of histone deacetylase 1 (HDAC1) by mitogens, recruitment of HDAC1 to the ERα promoter and increases in ERα transcription in breast cancer cells." (PMID 32054043, 2020). "In multivariate Cox regression analysis, HDAC1, HDAC2, or cytoplasmic HDAC3 was still an independent prognostic factor for the overall survival of breast cancer patients after correction for tumor size, histological grade, lymph node status, ER and PR." (PMID 32686908, 2020). "It should be noted that some genes highly related with breast cancer rank at top but are missed by the NCG4.0 such as the CREBBP, RHOA, HDAC1, ATM and MYC." (PMID 31088372, 2019). "Extending analyses to other non-sirtuin deacetylases, we found that DVL-1 co-precipitates with HDAC1, a class I histone lysine deacetylase (HDAC), which is over-expressed in breast cancer cells." (PMID 31700102, 2019). "The HDAC1 and HDAC3 inhibitor—MS-27—sensitized tumor necrosis factor-related apoptosis-inducing ligand (TRAIL)-resistant breast cancer MDA-MB-468 cells, inhibited angiogenesis and metastasis, and reversed EMT in vivo in xenografted BALB/c nude mice." (PMID 30691229, 2019). "For example, HDAC1 and HDAC2 are highly expressed in breast cancer and promote tumor progresses, and LSD1 is lowly expressed in breast cancer and inhibits tumor progress." (PMID 30310855, 2018). "BRMS1L-induced FZD10 epigenetic silencing through HDAC1 recruitment and histone H3K9 deacetylation at the promoter can suppress breast cancer metastasis by inhibiting aberrant activation of WNT3-FZD10-β-catenin signaling." (PMID 30286088, 2018). "The effect of HDAC inhibitor, trichostatin A (TSA), on Nav1.5, nNav1.5, HDAC1, HDAC2, HDAC3, REST, MMP2 and N-cadherin gene expression and on cell motility and migration of the less metastatic human breast cancer cells, MCF-7, were investigated." (PMID 28785170, 2017). "The expression patterns of HDAC1, HDAC2, and HDAC3 have been evaluated in different types of cancers, including gastric cancer, liver cancer, prostate cancer, breast cancer, renal cell cancer, ovarian and endometrial carcinomas." (PMID 28785170, 2017). "In doing so, the expression level of Nav1.5, nNav1.5, REST, HDAC1, HDAC2, and HDAC3 were measured and compared between the less aggressive human breast cancer cells, MCF-7 and the aggressive, MDA-MB-231 cells." (PMID 28785170, 2017). "We proved that G9a operates as a negative regulator of HEPH expression via YY1 and HDAC1 interaction, and is recruited to the HEPH promoter during breast cancer cell growth." (PMID 28819251, 2017). "In agreement with our results HDAC1 siRNA inhibited invasion by decreasing MMP9 mRNA expression, while overexpression of HDAC1 increased invasion and MMP9 expression in breast cancer." (PMID 28624794, 2017). "This study focused on examining the role of REST, HDAC1, HDAC2, and HDAC3 on influencing the expression of Nav1.5 and nNav1.5 in breast cancer that promote aggressiveness." (PMID 28785170, 2017).
breast cancer (continued). "By interaction with transcription factors and chromatin modifiers such as ER-alpha and histone deacetylase inhibitor HDAC1/245, 46, MIER1-alpha inhibits estrogen dependent growth and lack nucleus internalization during breast cancer progression." (PMID 28725034, 2017). "The most interesting crosstalk between breast cancer cell proliferation and maspin offers two interactions of maspin: with IRF6 transcription factor and with HDAC1 in a GST-dependent manner." (PMID 24581141, 2014). "In breast cancer, high (IRS 9–12) nuclear expression of HDAC1, HDAC2 and HDAC3 was observed in 32.7%, 24.1% and 31.7% of cases, respectively." (PMID 23627572, 2013). "Our study demonstrates a differential expression of HDAC1, HDAC2 and HDAC3 using immunohistochemistry in breast cancer." (PMID 23627572, 2013). "Chidamide, a selective inhibitor targeting HDAC1, HDAC2, HDAC3, and HDAC10, has been approved for treating relapsed/refractory peripheral T cell lymphoma and hormone receptor-positive, HER2-negative breast cancer after endocrine therapy." (PMID 41049003, 2025). "Molecular docking confirmed the strong binding affinity of St.10 to HDAC1, while in vitro and in vivo studies highlighted its potent anti-breast cancer activity with no systemic toxicity." (PMID 41440016, 2025). "In a more recent study, Βhura and colleagues performed the molecular docking assay for basil polysaccharides, in order to find out the binding potential against different epigenetic targets of breast cancer, including histone deacetylases (HDAC), HDAC1-2, 4–8, and histone acetyltransferases (HAT)." (PMID 41462669, 2025). "More recently, corin, a hybrid agent derived from the HDAC inhibitor entinostat and a tranylcypromine analog LSD inhibitor, has also been identified as a dual inhibitor of both HDAC1/2 and LSD1 with efficacy in several cancers including melanoma and breast cancer." (PMID 39912718, 2025). "Our results are in line with the previously reported worse survival rate of cancer patients with overexpressing class I HDACs, especially HDAC1 and HDAC3 in lung cancers, HDAC2 in liver or breast cancers, and HDAC1/2/3 in ovarian cancers, gastric cancers, or sarcomas." (PMID 39063083, 2024). "Furthermore, our result indicated an expressional decline of epigenetic machinery HDAC1 and DNMT3A in mammary tumor tissue because of combinatorial treatment." (PMID 38802425, 2024). "Distinct to nuclear receptors, the canonical and the noncanonical SIN3 complex coordinates with its respective corepressors HDAC1/2 and coactivator MLL1 to control their unique sets of genes in breast cancer cells, and SAP30 plays a determinant role in this coordination." (PMID 37655663, 2023). "Taken together, these findings indicate that HDAC1/2-mediated SIN3/SAP30 corepressor function is not essential for breast cancer progression." (PMID 37655663, 2023). "Although, either silencing of DNMT1 or inhibition of HDAC1 & HDAC2 were able to reduce cell migration even after 24 h, both knockdown of DNMT1 and TSA treatment synergistically inhibited migration of MDA-MB-231 breast cancer cells significantly higher." (PMID 36774386, 2023). "Conversely, knockdown of endogenous HDAC1 promoted an EMT-like phenotype in breast carcinoma organoids even in the absence of exogenous TGFβ." (PMID 37414747, 2023). "Tang and co-workers demonstrated that HDAC1 can positively regulate the transcription and promoter activities of IL-8, while not IL-6, in breast cancer cells." (PMID 35053925, 2022). "Our result was consistent with previous study that CHES1 only interacted with HDAC1 in ERα + breast cancer but not TNBC." (PMID 36450706, 2022). "Conversely, silencing NKX2-8 drastically increased, but overexpressing NKX2-8 decreased, the enrichment of H3K27 acetylation (H3K27ac) on the promoter of PTHrP gene in breast cancer cells, which demonstrated that NKX2-8 inhibited PTHrP expression via HDAC1 to reduce H3K27ac on the promoter of PTHrP." (PMID 35707355, 2022).
breast cancer (continued). "We performed IHC analyses on two breast cancer tissue chips containing a total of 87 patients with TNBC, showing that tumors with high KLF5 protein expression levels were significantly correlated with HDAC1 expression." (PMID 35342356, 2022). "Herein, we demonstrated that NKX2-8 transcriptionally downregulated the PTHrP expression through directly interacting with histone deacetylase 1 (HDAC1) on the PTHrP promoter, resulting in a reduction of histone H3K27 acetylation, which transcriptionally downregulated PTHrP level in breast cancer." (PMID 35707355, 2022). "Increased expression of HDAC1, HDAC2, HDAC3 and HDAC6 are reported in several cancers including colon, prostate and breast cancer and inhibition of HDACs potentially could target proliferation, differentiation, angiogenesis, and migration." (PMID 33802026, 2021). "To explore the molecular basis of PPP3CB downregulation, we first considered an epigenetic mechanism as we showed that a class I histone deacetylase (HDAC) inhibitor, entinostat (SNDX-275 or MS-275) mainly inhibited HDAC1 and potently induced apoptosis in HER2-positive breast cancer cells." (PMID 33976188, 2021). "Since HDAC1, HDAC2, and HDAC3 are the most common histone deacetylases in human tissues with a relatively high abundance and have already been reported elsewhere to be potential oncogenes in breast cancer, our studies mainly focus on these three HDAC proteins." (PMID 32686908, 2020). "Thus, HDAC1, HDAC2, and HDAC3 all displayed typical oncogenic characteristics and were important in the early development of breast cancer and later survival of patients." (PMID 32686908, 2020). "Prior to VPA/hydralazine treatment, DNMT3a, DNMT1 or HDAC1 expression was not different in the mammary tumors of HF offspring, compared with controls." (PMID 31889127, 2019). "In this study we aimed to investigate the impact of combinatorial SFN and WA on MCF-7 estrogen receptor-positive (ER (+)) and MDA-MB-231 ER (−) breast cancer cell proliferation in conjunction with their role in the epigenetic gene expression of DNMT1, DNMT3A, DNMT3B and HDAC1." (PMID 28534825, 2017). "Interestingly, it is likely that this combinatorial dietary regimen is more effective in regulation of DNMT1 expression in breast cancer MDA-MB-157 cells than MDA-MB-231 cells, which is opposite to what we have found in HDAC1 expression." (PMID 28839265, 2017). "Previous studies have shown that Pargyline, a nonspecific inhibitor of LSD1, interfered with the EMT of prostate cancer in vivo, and the lysine-specific demethylase UTX inhibited EMT-induced breast cancer stem cell properties by epigenetic repression of EMT genes in cooperation with LSD1 and HDAC1." (PMID 29088714, 2017). "PN was reported to specifically deplete HDAC1 protein in breast cancer cells without affecting other class I/II HDACs." (PMID 26824319, 2016). "As compensatory responses in protein expression are reported between the HDAC1 and HDAC2 isoenzymes in conditional knockout mice, and on siRNA depletion in osteosarcoma and breast cancer cell lines, we tested if this was also the case in A549 lung cancer cells." (PMID 25970771, 2015). "Finally, we report a significant correlation between MBP-1, HDAC1 and ERBB2 protein expression in primary breast carcinomas." (PMID 23421821, 2013). "Studies have also shown that disruption of transcriptional repressor multi-molecular complex, HDAC1/DNMT1/SUV39H1, is associated with ERα transcriptional activation in ERα-negative breast cancer cells." (PMID 22662208, 2012). "In sum, the loss of HDAC1 and HDAC2 increases C3 and NCOA2, but not CLU, ERBB2, MYC, or PGR, providing evidence that C3 and NCOA2 are repressed in breast cancer cells by the HDAC1/2 components of the Sin3A repressive complex." (PMID 20920219, 2010).